ATRX (ATRX chromatin remodeler)
Diseases named in the same sentence as ATRX in open-access papers (continued):
Sharing a sentence is not in itself a finding about the gene and the disease.
infection (continued). "Using Western Blot experiments from iSLK cells infected with high multiplicity of infection (MOI), we could demonstrate that KSHV infection leads to a reduction of ATRX protein levels." (PMID 24453968, 2014). "Furthermore, ATRX knockout does not significantly affect viral genome accessibility in the first 4 h of infection." (PMID 41012597, 2025). "Our work mechanistically describes the antiviral function of ATRX and introduces a novel, pro-viral role for this protein, perhaps explaining why, unlike during infections with other herpesviruses, it is not directly targeted by a viral countermeasure in HCMV infected cells." (PMID 39236084, 2024). "However, at later times post infection, ATRX was required for H3.3 occupation at the same site with no requirement for HIRA." (PMID 33909709, 2021). "However, changes in viral chromatin density in ATRX-KO cells are not observable until after 4 hr post infection, so we do not believe the observed to be effects to be the consequence of enhanced global histone mobility." (PMID 30465651, 2018). "Similar to our observation after de novo infection, KSHV lytic induction leads to a decrease of ATRX in cells expressing RFP; it is also able to overcome an apparent initial increase in ATRX expression after sodium-butyrate treatment of cells, which can be seen in cells with GFP-expression alone." (PMID 24453968, 2014). "Interestingly, the increased number of viral genomes synthesized in ATRX-depleted cells were not efficiently packaged, indicating the ATRX-mediated restriction to HCMV viral DNA replication may benefit productive infection by increasing viral fitness." (PMID 39236084, 2024). "During infection with HSV 7134, rather than forming aggregates, ATRX localizes to replication compartments, as marked by staining for HSV DNA binding protein ICP8, by 6 hpi." (PMID 33909709, 2021). "We conclude that HIRA does not stably colocalize with input vDNA or PML-NBs under infection conditions in which key intrinsic PML-NB restriction factors (PML, Sp100, Daxx, and ATRX;) rapidly entrap and silence vDNA following its nuclear entry." (PMID 30901352, 2019). "Knock-down experiments in primary human cells show that KSHV-infection is restricted by the ND10 components PML and Sp100, but not by ATRX." (PMID 24453968, 2014). "Nevertheless, it was demonstrated by confocal microscopy in a recent study by the Knipe lab that IFI16 and ATRX independently localize to EdC-labelled HSV-1 genomes as early as 15 min and until 60 min post infection, but viral heterochromatin formation was independent of IFI16." (PMID 31500286, 2019).
CNS tumors (15 papers, 2013 to 2025). "Rather, ATRX mutations in CNS tumors seem to develop in the context of other more basic genetic drivers to facilitate tumorigenesis." (PMID 31462295, 2019). "Mutations of ATRX (or lack of protein expression) have been linked to the ALT mechanism, and mutations of the promoter of TERT result in upregulation of the telomerase, both events being mutually exclusive in CNS tumors." (PMID 32642724, 2020).
neurodevelopmental disorder (5 papers, 2014 to 2022). A behavioral and cognitive disorder with onset during the developmental period that involves impaired or aberrant development of intellectual, motor, or social functions. "We now investigated possible functional links between TCF4, MEF2C, ZEB2, UBE3A and ATRX which are all implicated in clinically overlapping, severe human neurodevelopmental disorders." (PMID 31988313, 2020).
genetic disorder (4 papers, 2013 to 2026). "Alpha-thalassemia X-linked intellectual disability (ATR-X) syndrome, is a rare genetic disorder, caused by mutations in the ATRX gene." (PMID 39741769, 2024). "The chromatin remodelling protein ATRX is associated with the rare genetic disorder ATR-X syndrome." (PMID 24386478, 2013).
adenocarcinoma (3 papers, 2021 to 2023). A common cancer characterized by the presence of malignant glandular cells. "ATRX deletion is crucial for ALT activation, as shown by the development of genuine ALT in adenocarcinoma cells after ATRX inactivation and subsequent loss of telomerase activity." (PMID 36860927, 2023). "We identified frequent CNVs of the ATRX and RB1 genes in NENs and key driver mutations of the ARID1A, PIK3CA, CTNNB1, and MYC genes in nNENs, especially adenocarcinomas." (PMID 34422662, 2021). "The molecular criteria have not been established for GI MiNENs since the molecular landscape has been suggested to pure adenocarcinomas and ATRX mutation has not been reported." (PMID 34422662, 2021).
benign tumors (2 papers, 2021 to 2024). "In this location, it has been proposed to use ATRX loss as a marker of the highly probable evolution of benign tumors toward malignancy." (PMID 33946962, 2021).
neurological disorders (2 papers, 2025). "Disruption of these functions elicits neuroinflammation and may contribute to the pathology of human neurological disorders caused by ATRX mutations." (PMID 40938932, 2025). "Among these various interacting genes, four (RAF1, BRD4, ATRX, and TKT) have been associated with syndromic congenital conditions involving craniofacial abnormalities, heart defects, and neurological disorders." (PMID 40525707, 2025).
epithelial neoplasm (1 paper, 2025). A benign or malignant neoplasm that arises from and is composed of epithelial cells.
hematological malignancies (1 paper, 2010). "Analysis of GRAF1/OPHN-1-L expression and correlation with ATRX activity deserves further studies in such hematological malignancies." (PMID 20602808, 2010).
ATRX also shares sentences with these, for which no sentence is quoted: pheochromocytoma (8 papers); endometrial cancer (4); anaplastic gliomas (3); autism spectrum disorder (3); lip (3); mucosal (3); pancreatic cancer (3); uterine corpus endometrial carcinoma (3); alpha-thalassemia myelodysplasia syndrome (2); anaemia (2); colon adenocarcinoma (2); Combined Immunodeficiency (2); Cornelia de Lange syndrome (2); diffuse intrinsic pontine glioma (2); folate deficiency (2); ganglioglioma (2); myelodysplastic syndrome (2); neurodegenerative disease (2); neurofibromatosis type 1 (2); pancreatic (2); pancreatic NEN (2); Pitt-Hopkins syndrome (2); X-linked intellectual disability syndrome (2); acinar cell carcinoma (1); acute lymphoblastic leukemia (1); adrenal tumor (1); Adrenocortical Carcinoma (1); Alpha-thalassemia - myelodysplastic syndrome (1); astroblastoma (1); ataxia-telangiectasia-like disorder (1).
A further 105 diseases each share a sentence with ATRX in 1 paper.